PRAME (PRAME nuclear receptor transcriptional regulator)
Diseases named in the same sentence as PRAME in open-access papers (continued):
Sharing a sentence is not in itself a finding about the gene and the disease.
tumor (continued). "Of note, PRAME dichotomization did not further stratify immune favourable (ICR high) tumours, suggesting that PRAME may be involved in regulating an immunosuppressive tumour microenvironment." (PMID 34612587, 2021). "Cancer testis antigens such as the well-studied NY-ESO-1 are expressed at different levels within a single tumor; hence, it is not unlikely that PRAME expression might also display intra-tumor heterogeneity." (PMID 31311081, 2019). "To verify whether dysfunctional T cells are enriched in tumor-specificities at this early time point, we took advantage of MHC dextramers to identify tumor-specific (WT1, PRAME, or EZH2) and control viral-specific (cytomegalovirus-CMV) CD8+ T cells from patients." (PMID 30911002, 2019). "Since PRAME is not normally expressed in most normal adult tissues, targeted molecular inhibition of the PRAME protein or immunotherapy directed against PRAME−expressing tumor cells may be well tolerated." (PMID 27486988, 2016). "Hence, PRAME's effect on differentiation may be independent of retinoid signaling and may relate to one of PRAME's other cellular activities, and subject to influence by intrinsic differentiation aberrations specific to cell lines/tumor type." (PMID 40101298, 2025). "In our case, the tumor showed positivity for S100 and SOX10 but was negative for common melanocytic markers such as HMB-45, Melan-A, and PRAME." (PMID 40636637, 2025). "Immunohistochemical studies showed that the tumor cells were negative for Melan-A, HMB-45, PRAME, cytokeratin, CD34, and Factor XIIIa." (PMID 40636637, 2025). "About 57% of PRAME-negative HCC samples lacked Axl, while 54% of PRAME-positive patients were Axl-positive as well, which exhibited a more advanced tumor stage and a higher incidence of vascular invasion and recurrence." (PMID 37173882, 2023). "Moreover, given the association of PRAME expression with favorable outcomes in hematological diseases, directly targeting PRAME by small molecule inhibitors or gene silencing might not be as beneficial as compared with cytotoxic targeting of the tumor cells expressing PRAME." (PMID 31311081, 2019). "A significant difference in expression between tumours from survivors and tumours from deceased patients was detected for ITGB3 (p = 0.005), but not for the other proteins, CLU (p = 0.15), PRAME (p = 0.62), and CAPG (p = 0.24)." (PMID 19775429, 2009). "We did not use the Akt inhibitors like GSK 690693 to confirm the PRAME overexpression-induced malignant behavior in the LSCC cell lines and primary tumor xenografts, contributing to enhance our hypothesis that PI3K/AKT/mTOR is involved in LSCC development." (PMID 36910848, 2023).
cancer (148 papers, 2004 to 2026). A tumor composed of atypical neoplastic, often pleomorphic cells that invade other tissues. "PRAME is normally expressed predominantly in the testis and becomes aberrantly expressed in a wide variety of cancer types, often associated with poor outcome." (PMID 38030788, 2024). "As previously discussed, many studies cite the positive association between PRAME expression and the prognosis of individual cancer types." (PMID 39451258, 2024). "Recently, PRAME expression has received much attention in some types of malignant tumor as a useful diagnostic marker due to its nature of being a cancer/testis antigen." (PMID 38132219, 2023). "Although the role of PRAME in tumorigenesis is associated with the type of cancer, many studies have supported our conclusion." (PMID 36980687, 2023). "PRAME is a CUL2 ubiquitin ligase subunit that is normally expressed in the testis but becomes aberrantly overexpressed in many cancer types in association with aneuploidy and metastasis." (PMID 37162820, 2023). "Although CRL2pVHL components are not traditionally considered oncogenes, they have been associated with cancer progression, often through interactions with alternative substrate-recognition subunits such as preferentially expressed antigen in melanoma (PRAME)." (PMID 35664333, 2022). "In fact, studies in the human cancer cells also revealed that PRAME is associated with Cullin E3 ubiquitin ligase complexes in the Golgi and plays a role in ubiquitylation of target proteins." (PMID 34074333, 2021). "The PRAME gene family is highly associated with cancer development and is used as a biomarker for identifying various forms of cancer." (PMID 33126848, 2020). "Accordingly, we performed a meta-analysis to accurately assess the association of the expression level of PRAME with clinicopathological features and cancer prognosis." (PMID 33381588, 2020). "In this study, we identified CT10 and PRAME as cancer-associated antigens expressed in a subset of HGUCs." (PMID 31485721, 2020). "Although PRAME expression has been linked with poor survival and a higher risk of metastasis in solid tumors, its biological role in cancer is not well understood." (PMID 30602372, 2019). "It has been reported that PRAME proteins are associated to self-renewal cell maintenance and are currently considered as potential target to hamper cancer cell proliferation." (PMID 27259239, 2016). "Members of the PRAME gene family encode leucine-rich repeat (LRR) proteins functioning as transcription regulators in cancer cells." (PMID 23565261, 2013). "Likewise, PRAME, a known repressor of the retinoic acid receptor, is implicated in promoting cancer cell growth and resistance to therapy." (PMID 40076569, 2025). "However, increasing evidence suggests that PRAME is linked to a cancer-promoting gene in various types of cancers." (PMID 36910848, 2023). "As a novel diagnostic biomarker, an elevated PRAME expression level was correlated with more advanced malignant disease and a higher risk of metastasis, suggesting its pivotal role in cancer progression, including replicative immortality, invasion, and metastasis." (PMID 33503926, 2021). "However, the role of PRAME in migration and invasion—an important hallmark of cancer progression—remains elusive." (PMID 30602372, 2019). "Preferentially Expressed Antigen in Melanoma (PRAME) is a cancer/testis antigen that is overexpressed in a broad range of malignancies, while absent in most healthy human tissues, making it an attractive diagnostic cancer biomarker and therapeutic target." (PMID 29029482, 2017). "PRAME may therefore serve as an intracellular sensor of pathogen associated molecular particles (PAMPs) or molecules associated with cancer-related inflammation." (PMID 20799951, 2010).
cancer (continued). "Interestingly, the upstream untranslated region of the PRAME locus contains an unusually long stretch of approximately 36 putative G-quadruplex (G4) forming sequences, which have been associated with transcriptional regulation and cancer." (PMID 38030788, 2024). "Furthermore, the increase in PRAME expression with more advanced disease and a higher risk of metastasis suggests that PRAME plays a role in the acquisition of various cancer hallmarks, including replicative immortality or stemness, and invasion and metastasis." (PMID 31311081, 2019). "In complete responders, skin lesion RNA sequencing after treatment, compared with baseline, identified increased inflammation (CXCL5, CXCL8, IL1A, COL1A1) and downregulated cancer markers (PRAME, S100B, MLANA, STK32A)." (PMID 42316430, 2026). "Because MUM frequently expresses cancer–testis antigens, such as PRAME or SLC45A2, yet remains immunologically “cold,” TCR-T provides a way to convert antigen expression into a therapeutic weak point." (PMID 41598579, 2026). "Additional trials, such as NCT03686124 and NCT04262466, are exploring engineered T-cell receptor therapies targeting PRAME in SS and other cancers." (PMID 40849585, 2025). "This selective expression in cancer tissue makes PRAME a promising target for cancer-specific diagnostics and therapeutics." (PMID 40227827, 2025). "Consistent with a report from other cancers, we demonstrate that PRAME regulates cell differentiation in KC." (PMID 40101298, 2025). "Some targets and coregulators of PRAME's activity in cancer (e.g., p14/ARF, EZH2) are mediators of immunological signaling." (PMID 40101298, 2025). "Vaccines against MAGEA3, NY-ESO-1 and PRAME can elicit cancer-specific T cell responses implying potentially increased immunogenicity of HNSCC in response to DAC treatment." (PMID 39608124, 2025). "SS is a promising candidate for some forms of immunotherapy due to its frequent expression of cancer-testis antigens, such as PRAME, NY-ESO-1, and MAGE-A4." (PMID 40849585, 2025). "PRAME expression has been recorded in other keratinocyte‐derived cancer types, including cervical SCC (cvSCC) and head and neck SCC (HNSCC)." (PMID 40101298, 2025). "The cancer–germline antigen termed preferentially expressed antigen of melanoma (PRAME) is overexpressed in B-ALL, and peripheral blood T cells from ALL-patients display strong responses to PRAME derived epitopes." (PMID 40550858, 2025). "It has been reported that PRAME interacts with retinoic acid receptors (RARs) to inhibit the RA signaling pathway for the transcriptional regulation of cancer cells." (PMID 38424516, 2024). "Multiple studies demonstrated increased PRAME expression to be associated with Class II UM, the more aggressive subtype, and associated with stage III-IV cancers." (PMID 39451258, 2024). "Preferentially expressed antigen in melanoma (PRAME) is a testis-selective cancer testis antigen with restricted expression in somatic tissues and re-expression in various cancers." (PMID 38315310, 2024). "In HCC, Axl induces the expression of PRAME through MAPK signaling, which causes the dedifferentiation of cancer cells, a loss of liver function and elevated cancer cell invasion." (PMID 38673795, 2024). "The PRAME promoter region is hypermethylated and silenced in somatic cells and PRAME(−) cancer cells, whereas it is hypomethylated in testis and PRAME(+) cancer cells." (PMID 38030788, 2024). "Taken together, these findings suggest that PRAME plays a role in regulating normal meiotic recombination and causes genomic instability when mis-expressed in somatic cells, which could explain the association between PRAME expression and aneuploidy in UM and numerous other cancer types." (PMID 38030788, 2024). "The newly described functions of PRAME in this study open new avenues for investigating its role in cancer progression and for leveraging therapeutic vulnerabilities created by its expression." (PMID 38030788, 2024).
cancer (continued). "NY-ESO-1, MAGEA4, PRAME, and SSX2 are potential cancer–testis antigens that have been associated with HL in various studies and tested in clinical trials." (PMID 38934093, 2024). "PRAME plays a role in the acquisition of various cancer hallmarks, including replicative immortality or stemness, invasion, and metastasis." (PMID 38315310, 2024). "Initially identified as a tumor antigen in human melanoma cells, PRAME was subsequently recognized as one of the cancer/testis antigens (CTAs) with roles in both immune response and reproduction." (PMID 38395975, 2024). "Nevertheless, the prominence of PRAME expression in malignancies and its low levels in healthy tissue render this protein a valuable biomarker for both cancer diagnoses and resection margins during oncology surgery." (PMID 39659431, 2024). "We confirmed that IMC-F106C recognized PRAME-pHLA on the cancer cell surface, redirected donor T cells, and efficiently mounted an anti-PRAME-specific antitumor response (i.e. CD8+ IFNγ release and cytolysis)." (PMID 39659431, 2024). "Currently, PRAME is being researched as a target for immunotherapy for cancer vaccines and T-cell-based therapies." (PMID 39451258, 2024). "It is known that immunotherapy has revolutionised the landscape of cancer treatment, and PRAME is emerging as a promising immunotherapeutic target." (PMID 38338862, 2024). "Due to its differential expression profile and critical role in cancer progression, PRAME has also garnered interest as a potential as a therapeutic target." (PMID 39091741, 2024). "Here, we shed new light on the functions of PRAME and reveal how misexpression of PRAME promotes genomic instability and aneuploidy, which are hallmarks of cancer." (PMID 38030788, 2024). "PRAME is a cancer-testis antigen that is normally expressed in the testis and is aberrantly overexpressed in many cancer types." (PMID 38030788, 2024). "In our cohort, we had one poorly differentiated carcinoma, and it showed a low percentage of PRAME expression as expected and as demonstrated in other studies." (PMID 39727621, 2024). "PRAME has been considered to be a significant target in immunotherapy due to its restricted re-expression in cancer." (PMID 36980687, 2023). "Screening of cancer germline antigens showed that PRAME was significantly upregulated, while antigen-presenting human leukocyte antigen (HLA) genes were downregulated." (PMID 37152992, 2023). "Although our study only included a limited number of advanced‐stage patients, higher PRAME expression in the advanced stage has also been documented in a pan‐cancer meta‐analysis." (PMID 37341056, 2023). "In contrast, it has also been shown that HDAC-independent mechanism (e.g., retinoic acid receptor signaling) regulates PRAME expression, thus leading to the development of cancer." (PMID 36910848, 2023). "Recently, the CTAs MAGEC2, CT45A1 and PRAME were also reported to influence the EMT phenotype in cancer cells by modulating the expression of EMT genes." (PMID 36980267, 2023). "PRAME is highly expressed in cancer, including hematological malignancies, and as a tumor-associated antigen (TAA), it represents a potential immunotherapy target." (PMID 36982699, 2023). "For instance, CUL2, RBX1, ELOB, and ELOC are known to interact with PRAME, a substrate-recognition subunit that is overexpressed in a variety of cancers, including HCC." (PMID 35664333, 2022). "Preferentially expressed antigen of melanoma (PRAME) is a leucine-rich repeat protein ectopically expressed in a broad spectrum of cancers, including KC." (PMID 35892887, 2022). "The cancer/testis antigen Preferentially Expressed Antigen in Melanoma (PRAME) is a promising target for ATCs since it is highly expressed in several solid tumor indications, while its expression in normal tissues is mainly restricted to the testis." (PMID 35454906, 2022).
cancer (continued). "We co-cultured tumor associated antigen (TAAs: SSX2, PRAME, MAGEA4, SURVIVIN, and NY-ESO-1) specific CD8+ T cells with partially HLA-matched cancer cells expressing SURVIVIN, MAGE-A3, and MAGE-A4." (PMID 35681750, 2022). "The Preferentially Expressed Antigen in Melanoma (PRAME) is a well-suited cancer/testis target antigen, having only a minor and selective expression pattern in healthy tissues." (PMID 35454906, 2022). "The four MM patients with SF3B1 mutation in our cohort showed a higher percentage of cells with PRAME expression, a cancer/testis antigen that is more heavily overexpressed in MDS." (PMID 36230837, 2022). "As a nuclear receptor transcriptional regulator, PRAME has been extensively studied in cancer biology and is believed to play a role in cancer cell proliferation by suppressing retinoic acid (RA) signaling." (PMID 34074333, 2021). "All these recent evidences support PRAME as a promising target for developing CAR-T-based immunotherapies using CARs that bind PRAME peptides bound to HLAs or the protein on cancer cells expressing it on their surface." (PMID 33804612, 2021). "Recently, expression of PRAME (Preferentially Expressed Antigen in Melanoma), a cancer-testis antigen, has been described as an independent biomarker for metastasis." (PMID 34209210, 2021). "Recent evidence has indeed shed light on PRAME as a cell-surface cancer biomarker and as a target for TCR mimic antibodies (TCRm), opening the possibility for effective CAR-based T cell therapies." (PMID 33804612, 2021). "PRAME helps cancer cells to survive by suppressing retinoic acid-driven apoptosis and inhibition of cell proliferation." (PMID 34195690, 2021). "PRAME, an antigen high-expressed in various types of cancers, is involved in cell apoptosis, differentiation, proliferation, and metastasis, and it had the greatest fold change in the two groups." (PMID 33612479, 2021). "PReferentially expressed Antigen in Melanoma (PRAME) is a cancer testis antigen with restricted expression in somatic tissues and re‐expression in poor prognostic solid tumours." (PMID 34612587, 2021). "The technique was used to label an antibody to PRAME, a cancer-testis protein overexpressed in a number of cancers." (PMID 34884647, 2021). "Despite extensive studies of PRAME in cancer biology, few reports have focused on the function of PRAME in spermatogenesis." (PMID 34074333, 2021). "Due to its highly restricted pattern of expression, PRAME has emerged as an attractive target for cancer immunotherapy, in which cytotoxic T lymphocytes are developed to selectively target and eliminate PRAME-positive cancer cells." (PMID 35076507, 2021). "PRAME was first identified as a cancer antigen recognized by HLA-A*24 restricted CTLs in metastatic melanoma." (PMID 33503926, 2021). "The PRAME gene is not only expressed in the normal testis but also widely expressed in numerous cancers." (PMID 34178030, 2021). "Numerous evidence also indicates that PRAME is membrane-bound in several cancer cells and that antibodies targeting the extracellular region 310–331 show effectiveness to detect cancers and potentially treat them through targeted therapies." (PMID 33804612, 2021). "In this review article, we discuss the potential roles and physiological functions of PRAME in various types of cancers." (PMID 32022332, 2020). "Given its preferential expression in cancer cells, PRAME attracted a lot of interest as a potential immunotherapy target." (PMID 33008022, 2020). "The overall results suggest that PRAME overexpression is an indicator of poor DFS in patients with cancer." (PMID 33381588, 2020). "The overall results suggest that PRAME overexpression is an indicator of poor PFS in patients with cancer." (PMID 33381588, 2020).